ICOS (inducible T cell costimulator)
Diseases named in the same sentence as ICOS in open-access papers (continued):
Sharing a sentence is not in itself a finding about the gene and the disease.
tumor (continued). "Anti-PD-1 and anti-CTLA-4 treatments both induce the expansion of specific subsets of tumor-infiltrating exhausted-like T cells, and anti-CTLA-4 additionally engages ICOS+ Th1-like CD4 T cells." (PMID 31182061, 2019). "Compared to other T cells, Tregs have an activated phenotype (ICOS, GARP, CD39, GITR, HLA-DR) and expand in situ through ICOS/ICOS-L interaction with tumor-infiltrating plasmacytoïd dendritic cells or tumor cells." (PMID 30922400, 2019). "In particular, tumor-infiltrating CD39+ Treg have high expression of surface molecules related to immunosuppression, such as ICOS, PD-L1 and CTLA-4." (PMID 30651930, 2018). "As already mentioned, recent cancer immunotherapies have targeted the molecules in the tumor microenvironment of immune check point inhibitors including CTLA4, PD-1 or ICOS." (PMID 29988281, 2018). "Elevated ICOS+ Tregs were also present in bone marrow of AML patients, indicating an active presence of these cells in the tumor microenvironment." (PMID 30319662, 2018). "Interestingly, ICOS/ICOSL axis could have a dual effect to participate in anti-tumor T cell response as well as a pro-tumor response connecting with Tregs’ activity, therefore both antagonist and agonist antibodies targeting this pathway could be effective for cancer treatment." (PMID 29988281, 2018). "Blockade of ICOS signaling by application of a blocking anti-ICOSL mAb impaired the interaction between Treg cells and tumor cells and improved disease." (PMID 30319662, 2018). "Similar to CTLA-4, the co-stimulatory receptors GITR, ICOS, and OX40 were consistently expressed on tumor-infiltrating Treg cells in mouse and human tumors." (PMID 29576375, 2018). "The phenotypic studies of tumor-infiltrating Treg in relation to CD39 expression were partly based on the immunosuppressive surface molecules analyzed; ICOS, PD-L1 and CTLA-4, which were all increased on CD39+ Treg." (PMID 30651930, 2018). "Together, miR21 increased interaction of Treg cells with endothelial cells via ICOS/ICOSL axis and stimulated tumor angiogenesis, which was interrupted by ABT-199 through targeting Bcl-2 expression on endothelial cells." (PMID 28637496, 2017). "Here, the authors show that Newcastle Disease Virus (NDV) upregulates the inducible co-stimulator (ICOS) on T cells and that intratumoral targeting of ICOS with engineered NDV in combination with CTLA-4 blockade induces systemic anti-tumour immunity in mice." (PMID 28194010, 2017). "With their immunosuppressive functions, Treg infiltration, and perhaps more importantly, ICOS+ FOXP3+ Treg infiltration, plays critical roles in tumour progression and clinical behaviour by modifying the host’s immune response." (PMID 27725696, 2016). "The cohort of 402 primary HNSCC tumor samples was evaluated for PD-L1 expression on TC and IC as well as for PD-1, LAG-3, and ICOS expression on IC." (PMID 27841362, 2016). "In contrast, in tumor-bearing control mice and mice treated only with anti-CTLA-4 where tumor burden was high, ICOS expression was increased on both FoxP3+ Tregs and FoxP3− Teff cells." (PMID 26961085, 2016). "In CRC patients with liver metastasis, the tumor-specific T cell response is comprised by high numbers of activated Tregs, expressing high levels of GITR and inducible T cell costimulator (ICOS)." (PMID 26605342, 2015). "Indeed, targeting ICOS may lead to improved anti-tumor responses with anti-CTLA-4 therapy." (PMID 24883190, 2014). "Engineered T cells activated by both tumor-specific TCR and costimulatory molecules such as CD28, 4-1BB, OX40, and inducible costimulator (ICOS) have enhanced antitumor activity to tumors." (PMID 25009822, 2014). "Furthermore, we found that effector CD4+ T cells, particularly Tbet+ICOS+ Th1-like CD4+ T cells, were important for the remodeling of tumor vasculature and the increase of TA-HEVs during anti-CTLA-4 therapy in the MCAprog tumor model." (PMID 40460830, 2025).
tumor (continued). "In contrast, the co-stimulatory receptor ICOS was significantly upregulated on B cells within the tumor microenvironment compared to non-tumor tissue." (PMID 41008839, 2025). "Therefore, the activities of anti-CTLA-4 antibodies on tumor-infiltrating Tbet+ICOS+ Th1-like CD4+ T cells and tumor vasculature are both governed by antibody Fc effector function." (PMID 40460830, 2025). "Indeed, anti–PD-1 therapy increased the levels of IL-21 in BALF of tumor-bearing aged mice, which was disrupted by ICOSL blockade, and lung-infiltrating ICOS+CD4+ T cells in anti–PD-1 Ab–treated aged mice had an ability to produce IL-21." (PMID 40198121, 2025). "Based on these interpretations, it is necessary to determine the dependency of ICOS on both irAE pathology and antitumor immunity, especially in terms of the infiltration of Tregs and CD4+ T cells into tumor sites and tissues with irAEs, and their ICOS expression." (PMID 40198121, 2025). "Additionally, this triple therapy increased the frequency of T-bet + CD8 + tumor-infiltrating lymphocytes (TILs) within the tumor microenvironment (TME), enhanced the frequency of CD4+ ICOS+ T cells, promoted granzyme B production, and reduced PD-1 expression." (PMID 41024300, 2025). "Of note, Foxp3+ Tregs did not efficiently infiltrate into the lung compared with effector CD4+ T cells, while tumor-infiltrating Treg cells highly expressed ICOS regardless of host age or anti–PD-L1 therapy." (PMID 40198121, 2025). "Increased ICOS-positive CD4+ and CD8+ T cells enriched in Icosl-KO tumor." (PMID 40708008, 2025). "Patterns of ICOS and ICOSL expression varied between and within tumor types." (PMID 40297627, 2025). "Likewise, ICOS and CTLA4 are primarily expressed by T cells, but are significantly higher in expression in tumour compared to pancreatic adjacent normal tissue in epithelial and endothelial cells." (PMID 39915477, 2025). "In addition, the proportions of ICOS+, LAG3+, 4-1BB+, and OX40+ tumor-infiltrating iNKT cells were higher compared with circulating iNKT cells from patients or HDs." (PMID 41562072, 2025). "While exhaustion markers, such as PD-1 and CTLA-4, remained stably expressed across tumor progression, co-stimulatory molecules, including CD28 and ICOS, were significantly downregulated by 6 weeks, highlighting a state of persistent checkpoint signaling coupled with a loss of co-stimulation." (PMID 41278869, 2025). "To directly address the contribution of diet-derived AhR ligands to effector functions, we analyzed the expression of co-stimulatory molecules ICOS and GITR by tumor-infiltrating effector CD8 T cells from mice fed on indole-poor or I3C diet, after anti-PD1 treatment." (PMID 41331250, 2025). "However, this advantage can be lost upon transition to the NSCLC tumor site, akin to PD1+CD28− T cells expressing ICOS." (PMID 39684559, 2024). "The functional advantage provided to peripheral CD28− T cells by ICOS has been confirmed in the peripheral blood but not at the tumor site of NSCLC cancer patients." (PMID 39684559, 2024). "We hypothesize that the increase in Tregs could inversely inhibit the ICOS/ICOSL signaling pathway, further suppressing effector T cell immune responses against the tumor and promoting CRC development." (PMID 39104717, 2024). "Besides maintaining homeostasis, F. prausnitzii was correlated with the immunostimulatory effects of ICI, increasing blood ICOS+CD4+ T cells and sCD25 serum levels as well as reprogramming of the tumor microenvironment." (PMID 38395948, 2024). "Furthermore, both in colorectal cancer (CRC) and non-small cell lung cancer (NSCLC), Duhen and colleagues demonstrated tumour-reactive CD4+ Th or follicular T helper (Tfh) TILs co-express PD1 and ICOS." (PMID 38440738, 2024).
tumor (continued). "The single non-Vδ1Vδ2 cluster present in the tumours had a high expression of CD45RO and Fas (CD95), and also a higher expression than most other clusters of several proteins expressed in activated cells, such as ICOS (CD254), OX-40 (CD134), CD25, and FoxP3." (PMID 38953978, 2024). "ICOS-mediated ICOSL triggering drives a “reverse signal” that inhibits migration and cytokine secretion in endothelial cells (ECs), dendritic cells (DCs), and tumor cells." (PMID 39104717, 2024). "Anti-ICOS Abs, including the humanized JTX-2011 (vopratelimab), have demonstrated significant antitumor efficacy and durable protection in preclinical syngeneic mouse tumor models." (PMID 39684559, 2024). "In preclinical studies, activating ICOS by an agonist is not sufficient to mediate anti-tumor effect, combining blocking inhibitory checkpoints and ICOS agonist mAbs should be considered as a promising strategy for improving efficacy for cancer immunotherapy." (PMID 38127899, 2023). "Therefore, neutrophil frequency and the phenotype of conventional T cells was investigated in tumor-bearing KB1P mice treated with anti–PD-1, anti–TIM-3, or anti-ICOS, as a systemic readout of increased IL-17A by γδ T cells." (PMID 36480166, 2023). "Moreover, risk scores were negatively related to the expression of CD274, CTLA4, ICOS, LAG3, PDCD1, and PDCD1LG2 and negatively correlated with CD8+, CD4+, and Treg tumor-infiltrating immune cells." (PMID 37674251, 2023). "Furthermore we assessed the presence of immune checkpoint biomarkers (IDO1, ICOS, LAG3 and PD-L1) on tumour epithelial and inflammatory cells across the sample tissues." (PMID 37527282, 2023). "The ICOS / ICOSL axis has dual effects, and it may be involved in anti-tumor T cell response and tumor promotion response due to its association with regulatory T cells (Tregs) inhibitory activity." (PMID 36855091, 2023). "As some level of T-cell activation may be expected in or around the tumor microenvironment (TME), we also evaluated ICOS mRNA expression in a range of cancer settings using TCGA database." (PMID 37593752, 2023). "Thus, the expression of ICOS and ICOSL in tumor tissues is relatively special and deserves more focus." (PMID 37850501, 2023). "A previous study based on different syngeneic tumor models has shown that CD8+ T cells co-expressing inhibitory receptors (IRs) are not dysfunctional, but rather highly express activation and effector-related marker genes such as IFNG, GZMB, MKI67, and ICOS." (PMID 37773254, 2023). "In the tumor-draining lymph node (tdLN) and bone marrow, significantly higher frequencies of CD431B11+CD4+ T cells but not CD431B11+CD8+ T cells in the PDOX treated mice were detected, and these cells differentially expressed ICOS, CD38, CD39, and KLRG1." (PMID 36796366, 2023). "Generally, ICOS is weakly expressed in normal nonlymphoid tissues; however, it is over‐expressed in T cells and T‐cell‐differentiating subsets within tumor tissues." (PMID 37850501, 2023). "In various tumor types, increased expression of the T‐cell costimulatory molecule (ICOS) on PBLs and TILs has been observed after CTLA4 blockade, suggesting that ICOS on immune cells may serve as a potential biomarker for anti‐CTLA‐4 therapy." (PMID 38045830, 2023). "Since ICOS engagement promotes ALK+ ALCL proliferation, it is tempting to speculate that by engaging its ligand (ICOS-L), tumor-specific ICOS subverts other critical co-stimulatory signals from immune cells, impairing cytotoxic response to tumor cells." (PMID 37810974, 2023). "Compared to the Treg cells in blood or adjacent normal tissue, Tregs in the tumor express higher levels of CTLA4, inducible T cell costimulator (ICOS) and tumor necrosis factor receptor superfamily member 9 (TNFRSF9; encoding 4-1BB), which reflect an activated state." (PMID 37187731, 2023).
tumor (continued). "While we did not observe upregulation of ICOS in the TDLN or tumor at early time points following treatment with radiation therapy, ICOS is expressed at baseline in both the untreated tumor and in T cells in the lymph node." (PMID 36056093, 2022). "In contrast, the involvement of ICOS-Fc in this mechanism is unlikely, since our previous work has shown that ICOS-Fc decreases IL-10 expression in the tumor mass when loaded into cyclodextrin nanosponges, but not in PLGA nanoparticles." (PMID 36500861, 2022). "The CD8+ PBMC cluster of Pop3 and Pop4 and CD4eff PBMC cluster of Pop0 and Pop4 were distinctly different to the other tissue types with lower expression of checkpoint markers (PD-1, ICOS, and CTLA-4), suggesting a less regulated immune tumor environment in the periphery." (PMID 35320356, 2022). "The tumor cells also expressed one or more of CD10, CXCR5, ICOS, and PD1 wherever available." (PMID 35299754, 2022). "And expression of ICOS and DES were significantly downregulated in tumor patients." (PMID 36406134, 2022). "However, PD-1 down-regulates ICOS on CD4+ T cells, which inhibits the differentiation of CD4+ T cells into Th1 cells and affects the anti-tumor response of Th1 cells." (PMID 36119047, 2022). "Complementary single-cell approaches show that a population of regulatory T cells co-expressing ICOS and IL-1 receptor type 1 is highly enriched in tumours but not in site-matched inflamed non-malignant tissue." (PMID 35545675, 2022). "Certain positive regulatory factors, such as CD27, CD28, CD30, ICOS, and negative regulatory factors, such as CTLA4, PD-1, BTLA, TIM3, andLAG3, at immune checkpoints affect the recognition and apoptotic ability of the immune system against tumour cells." (PMID 36118669, 2022). "Moreover, rare intratumoral CXCR5+PD1+ICOS+ TFH and CD4+CD25+CD127− Treg cells were more frequent in the tumor than the normal liver tissue." (PMID 35724271, 2022). "Multiple costimulation modules (e.g., CD2, ICOS, and YMFM-CD28) may benefit CAR-T cell functionality and help counteract the acquired mechanism of tumor resistance and tumor-dependent CAR-T cell suppression." (PMID 35205827, 2022). "The crosslinking of ICOS and ICOSL has stimulating activities, promoting an anti-tumor response by Th1, CTL and T follicular helper (Tfh) and a pro-tumor response mediated by Tregs and Th2 cells in the tumor microenvironment." (PMID 36591244, 2022). "In CLR, direct communication between T cells and macrophages that express activity markers such as ICOS were frequently found in tumor boundary areas but not the bulk tumor areas." (PMID 36376874, 2022). "A recent study showed that osteopontin (OPN) could bind ICOSL to promote tumor metastasis, whose interaction with ICOSL triggers different effects than those triggered by ICOS." (PMID 36405702, 2022). "Effector genes such as GZMB, GZMH and KLRG1 were the marker genes in clonotypes shared by all tissues, while the clonotypes present only in tumor showed upregulated T-cell exhaustion genes (HAVCR2, LAG3, CTLA4, TIGIT, PDCD1, and ICOS) and activation genes (SELL and TNFRSF9)." (PMID 36185254, 2022). "Interestingly, while the number of T cells remained unchanged in the tumor and lymph organs, those found in the tumor and TDLN following NTP treatment expressed more activation (ICOS+/PD1+, IFN‐γ) and less exhaustion (Tim3+/PD1+) markers." (PMID 36176603, 2022). "In addition to CD11c, antigen presenting (HLADR and β2M), costimulatory molecules (CD40, ICOS) as well as STING and CD68 were all upregulated in tumor compared to TAS." (PMID 36230846, 2022). "Th2 and Th17 CD4 T cells are not always considered a positive feature of tumor environments; however, patients with tumors expressing increased proportions of ICOS-expressing CD4 T cells have an improved prognosis." (PMID 36056093, 2022). "In tumor tissue, Methylibium demonstrated significant negative correlations with ICOS and TBX21 expression and with T-cell abundance." (PMID 33863341, 2021).
tumor (continued). "Inducible T‐cell co‐stimulator (ICOS) belongs to the B7‐CD28 immunoglobulin superfamily, which has dual role in different malignancies, and might participate in anti‐tumour T cell response as well as a pro‐tumour response." (PMID 33949771, 2021). "Moreover, angiogenesis and tumor metastasis are increased, both in vitro and in vivo, by OPN-mediated triggering of ICOSL, whereas they are inhibited by ICOS-mediated ICOSL triggering." (PMID 35052731, 2021). "Following pembrolizumab therapy, the TME of responders becomes activated, as evidenced by the increased immune activation gene score, increased frequency of ICOS+ and Ki-67+ CD4+ T cells, and a local enrichment of tumor cells with dendritic cells (CN-5) and CD4+ T cells (CN-8)." (PMID 34795254, 2021). "Surface markers (PD1 and ICOS) had similar expression panels in tumors and spleens, and significantly different expression levels of functional effectors (CXCL13 and IL-21) reflected the diverse status of tumor-infiltrating Tfh cells exposed to tumor antigens." (PMID 34359579, 2021). "Nevertheless, and despite high densities of T cells and TLS, only a small fraction of CD4+ and CD8+ T cells in the inflamed phenotype expressed the co-stimulatory receptors ICOS or 41BB, which co-ocurred with a significantly decreased MHC-II expression by tumor cells." (PMID 34580291, 2021). "Finally, 19 prognostic genes were verified by GSE17536 and GSE17537 from GEO, and five genes (ADAM23, ARHGAP20, ICOS, IRF4,MMRN1) were significantly different in tumour tissues compared with normal tissues at the protein level." (PMID 33949771, 2021). "Analysis of surgical tissues and peripheral blood before and after treatment showed that anti-CTLA-4 treatment could induce ICOS pathway activation, and CD4+ICOS+T cells could produce IFN-γ and recognize tumor antigens." (PMID 32864131, 2020). "In addition, iCOS-iCOSL are known to be involved in T-cell skewing, and reduced SOD expression is related to impaired CD8+ T cell responses in tumor infiltrating lymphocytes." (PMID 33552042, 2020). "Tumor-infiltrating CD8+CXCR5+ T cells also highly express PD-1 and ICOS, which may indicate that blocking CD8+ T cell immune checkpoint inhibitors could serve as a therapeutic option in the future." (PMID 31663864, 2019). "In this study, we determined 11 immunomodulators that are involved in tumor escape mechanisms and found 9 immunomodulators (LAG-3, TIM-3, CTLA-4, IFN-γ, ICOS, ICAM-1, TIGIT, NKG2A, and VISTA) that were upregulated in both high-immune score group and high-stromal score group." (PMID 31781309, 2019). "We propose that a panel comprising the markers CD45RA, CCR7, CD95, CD69, CD57, PD-1 as well as CD28, CD40L, and ICOS should be validated in larger cohorts of patients and used to develop a model aiding in the identification of NSCLC patients prone to show tumor regression upon anti-PD-1 therapy." (PMID 31176366, 2019). "We previously have revealed that there were more pDCs and ICOS+ Tregs in GC patients both in circulating and tumor tissue when compared with health population and ICOS+ Tregs in stage III and IV patients' tumor and peritumor tissue were significantly increased than that of stage I and II patients'." (PMID 31777600, 2019). "Other studies also showed that cytokine IL-4 and IL-10 expression is reduced and the tumor immune response is decreased by inhibiting the expression of ICOS and its receptor, which is not conducive to activation of T cells." (PMID 29316975, 2018). "Furthermore, agonists of stimulatory checkpoint pathways such as OX40, ICOS, GITR, 4-1BB, CD40, or molecules targeting tumor microenvironment components like IDO or TLR are under investigation." (PMID 29544515, 2018). "In here, Tregs expressing CTLA-4, ICOS, ENTPD1, CD45RA and PD-1 were the majority among tumoral Tregs and the so called effector Tregs, CD25hiFOXP3hiCD45RA- highly suppressive cells, were the most represented among tumor Tregs tissue derived." (PMID 29100374, 2017).